KLK3 (kallikrein related peptidase 3)
Description:
Hydrolyzes semenogelin-1 thus leading to the liquefaction of the seminal coagulum.
Synonyms: PSA; APS; KLK2A1; hK3
Tractability: Small molecule: a structure with a bound ligand is known; it has a binding pocket of medium quality; it belongs to a druggable protein family. Antibody: a drug acting on it is in phase 2 or 3 trials; its Gene Ontology location is reachable by antibodies, with high confidence; UniProt places it where antibodies can reach, with medium confidence; UniProt predicts a signal peptide or a membrane-spanning region. PROTAC: ubiquitination databases record sites on it; a small molecule that binds it is known.
Target class: Serine protease; Enzyme; Serine protease PA clan; Serine protease S1A subfamily; Protease
Gene: Protein-coding gene on chromosome 19 (50,854,915 to 50,860,764, forward strand). Ensembl gene ENSG00000142515.
Subcellular location: Secreted
Pathways (Reactome):
Metabolism of proteins: Regulation of Insulin-like Growth Factor (IGF) transport and uptake by Insulin-like Growth Factor Binding Proteins (IGFBPs)
Signal Transduction: Activated PKN1 stimulates transcription of AR (androgen receptor) regulated genes KLK2 and KLK3
Gene Ontology:
Molecular function: endopeptidase activity; hydrolase activity, acting on carbon-nitrogen (but not peptide) bonds, in linear amides; protein binding; serine-type endopeptidase activity; serine-type peptidase activity
Biological process: positive regulation of antibacterial peptide production; proteolysis; negative regulation of angiogenesis; regulation of systemic arterial blood pressure; zymogen activation
Cellular component: extracellular exosome; extracellular region; nucleus; protein-containing complex; secretory granule
Genetic constraint (gnomAD): Loss-of-function variants: 20 observed, 27.28 expected, observed/expected ratio (o/e) 0.73, 90% interval 0.51 to 1.07. The upper end of that interval is the gene's LOEUF score, 1.07, which puts it in group 4 of 6, group 1 being the genes least tolerant of losing a copy. Missense variants: 310 observed, 339.31 expected, observed/expected ratio (o/e) 0.91, 90% interval 0.83 to 1. Synonymous variants: 138 observed, 134.27 expected, observed/expected ratio (o/e) 1.03, 90% interval 0.89 to 1.18.
Homologues: Orthologues: chimpanzee KLK3 (98% identical), macaque KLK3 (90% identical), pig KLK1 (59% identical), mouse Klk1b21 (56% identical), mouse Klk1b11 (56% identical), mouse Klk1b1 (56% identical), mouse Klk1b22 (56% identical), mouse Klk1b24 (55% identical), mouse Klk1b27 (55% identical), mouse Klk1b3 (54% identical), mouse Klk1b5 (53% identical), mouse Klk1b9 (53% identical), and 18 more. Paralogues in human: KLK2 (77% identical), KLK1 (61% identical), KLK5 (40% identical), KLK14 (39% identical), KLK7 (39% identical), KLK8 (39% identical), KLK11 (38% identical), KLK12 (38% identical), KLK4 (36% identical), PRSS58 (30% identical), TMPRSS4 (29% identical), PRSS54 (20% identical).
Diseases named in the same sentence as KLK3 in open-access papers:
KLK3 is named in the same sentence as 275 diseases in open-access papers, as found by Europe PMC text mining. Sharing a sentence is not in itself a finding about the gene and the disease. The quoted sentences say what the papers report.
prostate carcinoma (2,545 papers, 1994 to 2026). A carcinoma that arises from epithelial cells of the prostate gland. "Type-2 diabetes had the largest number of protein contributions (184 proteins) whilst three conditions had only one protein generating their risk scores: motor neuron disease (NEFL), prostate cancer (KLK3) and endometriosis (PAEP)." (PMID 40594723, 2025). "Studies have shown that increased expression of the KLK3 gene in prostate cancer is linked to several processes such as cell growth, movement, infiltration, blood vessel formation, and resistance to cell death." (PMID 40388455, 2025). "The PSA (KLK3) genetic variant rs17632542 is associated with reduced prostate cancer risk and lower serum PSA levels, although the underlying reasons are unclear." (PMID 39505858, 2024). "Benign prostatic hyperplasia, prostate cancer, prostatitis are common conditions among others that can cause increase in KLK3 levels." (PMID 39390134, 2024). "The KLK3 gene encodes the prostate-specific antigen, which is widely used in the screening of prostate cancer." (PMID 32295536, 2020). "The KLK3 rs17632542 T>C is a nonsynonymous polymorphism with an amino acid change from isoleucine to threonine and has an association with prostate cancer risk as well as with the PSA level." (PMID 31861307, 2019). "In prostate cancer, a probable role of miR-3162-5p in the mechanism underlining the increased prostate cancer risk with the kallikrein-related peptidase 3 (KLK3) rs1058205 miRSNP T-allele has been demonstrated." (PMID 31769433, 2019). "Kallikreins have shown promise as diagnostic biomarkers, including KLK3, which is widely used for screening of prostate cancer and have been associated with prognosis and mortality." (PMID 29707153, 2018). "Kallikrein‐related peptidase 10 (KLK10) is homologue to KLK3 and encodes the prostate‐specific antigen, which is a widely used biomarker for the detection and monitoring of prostate cancer." (PMID 29377588, 2018). "Levels of KLK3 are commonly used for diagnosing prostate cancer, and the somatic mutation altering miRNA targeting of KLK3 was identified in prostate cancer." (PMID 23091610, 2012). "Both a somatic mutation (chr19:g.51363764A>C) and a germline mutation (rs1803136) in the 3′UTR of KLK3, a gene whose expression is commonly used as a diagnostic marker in prostate cancer, disrupted predicted target sites for miR-675, miR-138, and miR-210." (PMID 23091610, 2012). "Many kallikrein genes were found to be differentially expressed in various malignancies, and prostate specific antigen (encoded by the KLK3 gene) is the best tumour marker for prostate cancer." (PMID 12439720, 2002). "In contrast, another study focused on prostate cancer revealed a decrease in the mRNA levels of AR and AR-V7 (constitutively active variants), along with their targets kallikrein-related peptidase 3 (KLK3), FK506-binding protein 5 (FKBP5), and NKX3, following MLN4924 treatment and NAE knockdown." (PMID 39623094, 2024). "Furthermore, both mutations, somatic and germline, of the 3′UTR KLK3 gene interfere with the binding of miRNA-675, miRNA-138, and miRNA-210, which promote the expression of the KLK3 gene in prostate cancer and regulate cancer proliferation." (PMID 37736898, 2023). "KLK3 (also known as prostate-specific antigen) is an outstanding member of the KLKs family as a diagnostic marker and therapeutic target of prostate cancer (PCa), and several medicines are approved and undergone clinical research for the treatment of PCa via targeting KLK3." (PMID 36193495, 2022). "Splice-disrupt variants on BRCA1, AKR1C3, and KLK3 is observed in all types of prostate cancer." (PMID 35286517, 2022). "Indeed, in prostate cancer tumors, high KLK3 expression has been found to be associated with low angiogenesis activity (as determined by CD34 staining) and microvessel density (determined by CD31 staining)." (PMID 34948344, 2021).
prostate carcinoma (continued). "A recent analysis of interactions between KLK3 single nucleotide polymorphisms (SNPs) and other SNPs to identify interactions associated with prostate cancer aggressiveness support the notion that KLK3 and VEGF-C concertedly are involved in the regulation of prostate cancer tumor angiogenesis." (PMID 34948344, 2021). "In addition, rs266849 near KLK3 was only weakly associated with prostate cancer risk (OR: 0.93 (95% CI: 0.89–0.98), P = 0.009)." (PMID 21390317, 2011). "For example, in prostate cancer cells, expression of KLK3 and KLK4 results in loss of E-cadherin and induction of expression of the mesenchymal marker vimentin, a hallmark of epithelial-to-mesenchymal transitions, which is a critical step for cancer metastasis." (PMID 21072173, 2010). "Transcripts of prostate cancer-associated biomarkers—kallikrein-related peptidase-2 and -3 (KLK2, KLK3), folate hydrolase 1 (FOLH1), and neuropeptide Y (NPY)—were detected in the platelets of cancer patients but not in those of healthy controls." (PMID 40332071, 2025). "The selective effects of PHD1 depletion on both FOXA1 protein levels and KLK3 transcription underscore its unique and functionally relevant role in modulating androgen receptor signaling pathways in prostate cancer." (PMID 40643528, 2025). "Treatment with SeNPs, Flutamide, or a combination of them significantly reduced KLK3 mRNA expression in all prostate cancer cell lines, confirming the tumor-inhibiting properties of these chemicals." (PMID 40388455, 2025). "The prostate cancer biomarkers PSA (also known as KLK3), PSMA, and PSCA were evaluated in six, four, and two papers, respectively." (PMID 40805181, 2025). "The results from this study emphasize the importance of incorporating NETO2, HPN, AR, and KLK3 as part of a comprehensive model for prostate cancer prognosis, pointing towards their potential to improve clinical outcomes." (PMID 40034593, 2025). "Recent investigations have shown that human kallikrein-related peptidase 3 (KLK3), a protease found exclusively in the prostate, can promote the advancement of prostate cancer and serve as a biomarker." (PMID 40388455, 2025). "All treatment groups reduced the expression of the prostate cancer biomarker KLK3, with only the flutamide group showing a significant change (p < 0.05)." (PMID 40388455, 2025). "KLK3 has been utilized in several research studies as a biological indicator for prostate cancer prognosis and as a target for therapy." (PMID 40388455, 2025). "For example, KLK3 has been widely used as a marker of prostate cancer in clinical screening, diagnosis, prognosis and monitoring." (PMID 40156045, 2025). "This test measures the mRNA levels of three cancer-related genes: DLX1 (a prostate cancer cell proliferation gene), HOXC6 (a prostate cancer progression gene), and KLK3 (a prostate cancer reference gene)." (PMID 41374944, 2025). "Previous studies have shown that KLK3 plays a critical role in inhibiting prostate cancer progression and restoring chemotherapy sensitivity, while PAGE4 has been reported to significantly enhance tumor cell responsiveness to gefitinib and other therapies." (PMID 41020875, 2025). "In contrast, we observed minimal differences in the levels of prostate and prostate cancer-associated proteins, including KLKB1, KLK2, KLK3, ACP3, and SLC45A3, which are markers of conventional adenocarcinoma of the prostate." (PMID 39910169, 2025). "KLK3 expression is regulated by androgens in prostate cancer, and androgen receptor signaling is known to be a key driver of both prostate and bladder cancer progression." (PMID 40427030, 2025). "For example, it is known that KLK3/PSA has been widely used in clinical practice as a biomarker of prostate cancer." (PMID 39116105, 2024).
prostate carcinoma (continued). "For instance, KLK3 eRNA (KLK3e) selectively enhances the expression of androgen receptor-regulated genes, thereby promoting the proliferation and metastasis of prostate cancer." (PMID 38289619, 2024). "The canonical prostate adenocarcinoma markers AMACR (p504s) and KLK3 (PSA) were robustly expressed in the castration‐resistant prostate cancer (CRPC) epithelia." (PMID 38483933, 2024). "KLK3 is the most extensively studied serum biomarker used for early prostate cancer screening, clinical staging, and therapeutic response monitoring." (PMID 39057404, 2024). "KLK3 is commonly used as a marker for AR activity and for monitoring the progression of prostate cancer." (PMID 39598420, 2024). "PSA, also known as human kallikrein 3 (hK3 or KLK3), is one of the earliest discovered serological prostate cancer (PC) indicators widely used in clinical interpretation of prostate cancer." (PMID 36832253, 2023). "Nearly all prostate cancer patients express elevated levels of prostate specific antigen (PSA) encoded by the gene KLK3 and is often considered as indicative marker of prostate cancer and or anomalous functioning of the prostate gland." (PMID 36831540, 2023). "Some KLKs are therefore used as tumor biomarkers; for example, KLK3 [prostate‐specific antigen (PSA)] serves as a biomarker for prostate cancer." (PMID 37609678, 2023). "Both cell lines were established from cells isolated from the lymph nodes of patients with prostate cancer, express the AR and regulate the KLK3 gene in response to androgens." (PMID 37082578, 2023). "AR activity (by means of the expression of its target KLK3) was consistently correlated with the expression of GNMT in the majority of prostate cancer datasets analyzed." (PMID 35197445, 2022). "Including measurements of serum prostate-specific antigens (PSA/KLK3) in the diagnosis of prostate cancer has led to a significant increase in the detection of early-stage PCa (Gleason < 6)." (PMID 36434610, 2022). "AR regulates the expression of genes that play an important role in prostate cancer such as KLK3, KLK2, TMPRSS2-ERG, IGFR-1, FKBP5, FOXp1, TACC2, and UGT1A1." (PMID 36551557, 2022). "We found that the prostate cancer-specific genes, including KLK3, KLK2, FOLH1, and ACPP, are expressed mainly in luminal cells." (PMID 36712886, 2022). "KLK3 eRNAs can also enhance androgen receptor‐dependent gene expression in trans in human prostate cancer." (PMID 35170113, 2022). "A seminal study tested the theranostic potential of hu5A10, a humanized mAb targeting free prostate-specific antigen (KLK3), in prostate cancer." (PMID 33995659, 2021). "The consequence of such regulation, together with other proposed activities of KLK3, in prostate cancer is yet to be fully determined." (PMID 34948344, 2021). "KLK3 is a secreted protease, more widely known as a prostate cancer marker, prostate-specific antigen (PSA)." (PMID 34948344, 2021). "Several cellular and xenograft model studies suggest that KLK3 promotes the growth of prostate cancer cells and tumors." (PMID 34948344, 2021). "Prostate-specific antigen (PSA), also known as human kallikrein 3 (KLK3), is currently widely used as the gold standard biomarker for screening and diagnosis of prostate cancer." (PMID 34359624, 2021). "KLK3 is also known for its role in EMT induction in prostate cancer cell line PC-3, and has been found to downregulate CDH1 and regulate the cytoskeleton and cell migration process." (PMID 34206049, 2021). "In this review, we concentrate on the proposed roles of KLK3 in the regulation of angiogenesis, with a special focus on prostate cancer." (PMID 34948344, 2021). "Especially the hormones, and more specifically androgens, such as testosterone, have a central role in prostate cancer and also in the regulation of KLK3 expression." (PMID 34948344, 2021). "Plotting the mean values of H2AFJ versus KLK3 RNA levels for the prostate cancer clusters showed a high correlation coefficient of 0.88." (PMID 34828271, 2021).
prostate carcinoma (continued). "In particular, violin plots indicated that both H2AFJ and KLK3 had the highest expression levels in prostate cancer epithelial clusters 3, 4, and 9, and showed the lowest expression in the basal cell epithelial cluster." (PMID 34828271, 2021). "For example, changes in KLK3 glycosylation patterns were observed in samples from patients with prostate cancer compared with benign prostatic hyperplasia." (PMID 34562451, 2021). "Prostate-specific antigen/kallikrein-related peptidase 3 (PSA/KLK3) is a serine protease produced by epithelial cells in the prostate gland that is used as a clinical serum biomarker to detect and monitor prostate cancer." (PMID 34206049, 2021). "Systemic administration of this compound at a dose of 10 mg/kg for three cycles of five consecutive days in nude mice with human prostate cancer xenografts showed minimal effect on tumor growth but led to significant reduction in serum KLK3 levels." (PMID 32529252, 2020). "The mean Ct value for KLK3 from patient samples was 31.2 which was close to the value of 1000 LNCaP prostate cancer cells." (PMID 32630458, 2020). "One of the immediate possibilities is the use of specific KLK3 inhibitors that were previously developed for prostate cancer patients." (PMID 32529252, 2020). "As expected, KLK3 Ct values strongly correlated with Ct values of other genes which have been reported to play a role in prostate cancer (i.e., PCA3, AMACR, TRPM8, MSMB and PSGR)." (PMID 32630458, 2020). "Of note, PSA is a member of the KLKs and is also known as KLK-3, and has been demonstrated, in prostate cancer cells, to promote the epithelial mesenchymal transition (EMT) and cell migration by decreasing E-cadherin levels." (PMID 32948029, 2020). "Most of the studies involved in generation of small molecule inhibitors of KLK3 were focused on their usage in targeted treatment of prostate cancer." (PMID 32529252, 2020). "Our results point to the fact that KLK1, KLK2, and KLK14 (only in recurrent prostate cancer tissues) are underexpressed in prostate cancer tissues, while KLK3, KLK4, KLK8, and KLK9 are overexpressed in both recurrent and non-recurrent tissues." (PMID 33150763, 2020). "It is important to remark on the presence in this list of KLK3 (PSA) as the broadly accepted prostate cancer marker and EpCAM, the molecule used for the isolation of CTCs in our approach and the one classically used for CTC isolation in carcinomas." (PMID 32630240, 2020). "Having demonstrated heterogeneous AR output within prostate cancer cell lines, we asked if similar, intra-tumoral heterogeneity is observed clinically by immunohistochemical analysis of KLK3 and AR expression in several primary cancers." (PMID 30644358, 2019). "For example, PSA/KLK3 is generally used for detection, prognosis and monitoring in prostate cancer, but has at most marginal effects on tumor growth." (PMID 31412811, 2019). "Previous work using a KLK3 promoter/GFP reporter (PSAP-eGFP) showed that LNCaP prostate cancer cells display varying levels of eGFP expression." (PMID 30644358, 2019). "In contrast, the expression of the prostate cancer marker genes KLK3 (p < 0.01), FOLH1 (p < 0.05), and PSCA (p < 0.05) was decreased in CTCs at CRPC relapse." (PMID 31877738, 2019). "The byproduct of KLK3 is Prostate Specific Androgen (PSA) which is used as a biomarker of prostate cancer." (PMID 30838019, 2019). "Three genes closely related to AR functions in prostate cancer, AR, KLK3 and MAPK3, are among the detected DE genes." (PMID 30367578, 2018). "For example, androgen receptor and prostate-specific antigen (PSA)/kallikrein 3(KLK3) expression can significantly vary between different regions within the same prostate carcinoma." (PMID 30090875, 2018). "As expected, prostate-specific KLKs (KLK2 and KLK3) were expressed only in the prostate cancer (LNCaP) cell line." (PMID 28414719, 2017).